Y_RNA (Y RNA )
Gene: Miscellaneous RNA gene on chromosome 20 (43,451,159 to 43,451,260, reverse strand). Ensembl gene ENSG00000206998.
Homologues: Orthologues: chimpanzee Y_RNA (100% identical), macaque Y_RNA (95% identical), dog Y_RNA (83% identical), tropical clawed frog Y_RNA (75% identical). Paralogues in human: Y_RNA (94% identical), Y_RNA (92% identical), RNY3 (91% identical), Y_RNA (91% identical), Y_RNA (90% identical), Y_RNA (89% identical), RNY3P1 (88% identical), RNY3P16 (88% identical), Y_RNA (88% identical), Y_RNA (87% identical), Y_RNA (86% identical), RNY3P14 (85% identical), and 99 more.